TWIST1 (twist family bHLH transcription factor 1)
Diseases named in the same sentence as TWIST1 in open-access papers (continued):
Sharing a sentence is not in itself a finding about the gene and the disease.
tumor (continued). "Next, we determined the TWIST1 protein level in 30 RBX1 up-regulated TNBC tumour tissues using western blotting." (PMID 35802537, 2022). "A previous study reported that miRNA-3163 exerted its tumor suppression function by downregulating TWIST-1 in NPC." (PMID 35490173, 2022). "Twist1 can bind directly to the E‐cadherin promoter and strongly inhibit E‐cadherin expression, indicating that Twist1 promotes tumor cell invasion and metastasis." (PMID 33772986, 2022). "Previous studies on SNAI1 and/or TWIST1 in EC mostly relied on their immunohistochemical evaluation in tumor cells in the context of clinical variables, and increased SNAI1 and TWIST1 expression has been linked to EC progression or poor prognosis." (PMID 36140779, 2022). "Twist1 is an evolutionarily highly conserved transcription factor, which is widely expressed in a variety of normal tissues and tumor cells and plays a regulatory role." (PMID 35372470, 2022). "Our transcriptomic data suggest an enrichment of M2 TAM and of myofibroblasts, the most abundant stromal cells supporting tumor progression, in TWIST1-positive xenografts." (PMID 35022561, 2022). "The tumor suppressive miR-186-5p can bind to twist basic helix-loop-helix transcription factor 1 (TWIST1) transcripts and inhibit their translation as the two RNAs are negatively correlated." (PMID 34440137, 2021). "For example, the overexpression of Twist1 has been shown to suppress the expression of E-cadherin, an important molecule in cell–cell adhesion, suggesting that Twist1 promotes tumor metastasis through the induction of EMT pathways." (PMID 34577566, 2021). "We then compared tumor volume and weight features of this TWIST1-CRISPR1 selected clone with the control cells, and it was found a similar result for AT84 and RBT3." (PMID 33466385, 2021). "TWIST1 staining was observed in cytoplasm and nucleus of tumor cells in all the obtained CRC samples." (PMID 33752711, 2021). "TWIST1 is known as one of EMT-TFs that plays some critical roles in the tumor growth’s initiation, invasion, and metastasis." (PMID 33752711, 2021). "The first work supports the concept that upregulation of an EMT activator (e.g., TWIST1) in invasive cells of the primary tumor induces dissemination." (PMID 34768901, 2021). "TWIST1 protein expression was also assessed in primary tumor samples corresponding to the MED1 and MED6 cell lines." (PMID 33948561, 2021). "Immunohistochemical (IHC) and western blot (WB) assay were used to detect the expression level of E-cadherin, N-cadherin, vimentin, and TWIST1 to evaluate the effect of QFG on tumor cell EMT progression." (PMID 34887935, 2021). "On the other hand, autophagy can be used as a tumor suppressor signal by selectively regulating key mediators such as p62, TWIST1, and beclin-1 to counteract the activation of EMT." (PMID 34887935, 2021). "Snai2, which is the most important member of the Snail family, can enhance tumor cell proliferation and invasiveness, whereas Twist1 can mediate EMT during cancer progression, particularly in the acquisition of metastatic potential." (PMID 32661742, 2021). "ZEB2 was elevated in ascitic cells, while the changes in ZEB1, Snail and Twist1 in ascites and primary tumours were mild." (PMID 34211089, 2021). "This complex is related to the nuclear location of Twist1, increasing the tumor cell plasticity and vasculogenic mimicry, and promoting metastasis." (PMID 34204259, 2021). "The tumor suppression effect is achieved partially by NKX3-1 repression of transcription of TWIST1, a gene with localized transcription in neural crest cells during vertebrate embryogenesis." (PMID 34595169, 2021).
tumor (continued). "Twist1 is a direct target of miR-203, with miR-203 acting as a tumor suppressor by negatively targeting Twist1." (PMID 33672684, 2021). "We knockout TWIST1 expression in tumor cells using the CRISPR/Cas9 and the success of the gene inactivation was confirmed by more than 95% at both protein and mRNA levels." (PMID 33466385, 2021). "Our results demonstrate that nuclear TWIST1 and cytoplasmic CD105 expressions in tumor cells had associations with more aggressive tumor behavior and more advanced diseases in CRC cases." (PMID 33752711, 2021). "Specifically, Twist1 was found to correlate with the thyroid differentiation score (TDS) and to associate with the histological variants, BRAF/RAS phenotype, tumor size, lymph node metastasis, and TNM stage." (PMID 34575184, 2021). "Since all PTCs retain a fairly differentiated phenotype, this data would seem to indicate that Twist1 is the factor that comes into play earliest in the dedifferentiative transformation of the tumor." (PMID 34575184, 2021). "Note that the Twist1 expression in tumor cells takes place under hypoxic conditions, which stimulate tumor cell dissemination to less hostile environments, presumably through the promotion of EMT." (PMID 34577566, 2021). "This study provides insight into the crosstalk between TWIST1 and CSF1 in metastatic OSCC and supports TWIST1-mediated macrophage activation to promote tumor invasion." (PMID 33466385, 2021). "They further demonstrated that circ-10720 knockdown represses the tumor-promoting activity of Twist1 in vitro and patient-derived xenograft." (PMID 34858485, 2021). "Among these upregulated PRC2+-CGI genes, we found many well-defined oncogenes and genes encoding tumor-promoting factors such as MYB, TWIST1, SYK, TEAD4, FOXC1, and FGFR3." (PMID 33931649, 2021). "High nuclear expression of the TWIST1 transcription factor was observed only in the MED1 primary tumor." (PMID 33948561, 2021). "Amongst the EMT-inducing transcriptional factors associated with metastasis and tumor invasion are Snail, Slug, dEF1, SIP1, Twist1, FOXC2, and Goosecoid." (PMID 33672684, 2021). "Findings indicated that CRC patients with positive TWIST1 expression in tumor cells have low survival rates." (PMID 33752711, 2021). "Collectively, these results demonstrated that ISL inhibited the tumor metastasis via up-regulating the E-cadherin and down-regulating the N-cadherin, p-Smad2/3, and TWIST1/2 protein expression in the xenograft animal model." (PMID 33799801, 2021). "BMI1 and TWIST1 function together to promote tumor dedifferentiation, metastasis, and development of drug resistance." (PMID 33927214, 2021). "Researchers suggested that turning off EMT‐inducing transcription factor Twist1 expression to allow reversion of the EMT is essential for disseminated tumour cells to proliferate and promotes colonization in distant sites." (PMID 34528373, 2021). "Twist1 overexpression has also been linked to self-renewal in mammary epithelial and cancer cell lines, indicating that Twist1 contributes to tumor stemness." (PMID 34577566, 2021). "For instance, at early metastatic stages, Twist1 contributes to tumour invasion and vascular intravasation through repression of E-cadherin expression." (PMID 34868979, 2021). "TWIST1 is well‐known for its essential role in tumor development, metastasis, and chemoresistance in a variety of cancers." (PMID 33470057, 2021). "Taken together, our data support the notion that the tumor suppressive activity of miR-145-5p on TWIST1 translation, consequently on EMT, self-renewal, and migration, depends on the CPEB1 expression status of the cancer cell." (PMID 33227047, 2020). "Oncomine datasets demonstrated CDH1, CDH2, SNAI1, SNAI2, VIM, TWIST1 in 20 types of cancers between tumor and normal tissues." (PMID 31915310, 2020). "(a) Schematic of the experiment to extract tumor associated macrophages from the primary tumors of MYC- (n = 5) and MYC/Twist1-HCC (n = 5)." (PMID 31933479, 2020).
tumor (continued). "Together, these results show that the RNA-binding AUF1 protein plays important roles in breast carcinogenesis through stabilization of the key transcription factors TWIST1 and SNAIL1, and the consequent induction of EMT as well as stemness features." (PMID 32759946, 2020). "Twist1 regulates tumor metastasis by inducing the epithelial-mesenchymal transition (EMT), a process in which epithelial cells acquire the motile and migratory characteristics of mesenchymal cells." (PMID 33381597, 2020). "In contrast, Klemke and colleagues found that Twist1 expression in human breast tumor cells promoted tumor cell adherence to the vascular wall through a β1 integrin-independent mechanism." (PMID 32391382, 2020). "Our results indicate that phosphorylation of S42 and T125 by AKT is essential for TWIST1-mediated tumor growth and metastasis." (PMID 32922123, 2020). "Further analysis of RDEB-tissues showed a strong expression of transcription factor TWIST1, a known upstream driver of miR-10b-mediated tumor malignancy." (PMID 32276641, 2020). "H19-derived miR-675 favors the tumor progression by repressing several well-known tumor suppressor genes, such as Rb, Twist1 or RUNX1." (PMID 32610610, 2020). "Clusters #2 and 3, which had high expression of mesenchymal genes including Vimentin, Timp1, and Twist1, were predominantly composed of recurrent tumor cells but had small populations of primary tumor cells." (PMID 33024122, 2020). "For instance, down-modulation of Twist1 in benign skin tumors diminished proliferative capacity paralleled by elevated apoptosis, and inhibited tumor maintenance and progression independently of its function during EMT." (PMID 33297508, 2020). "(g) Representative images from IHC staining for MYC and F4/80 in MYC/Twist1 HCC in temporal sequence from early tumor (n = 5) to later tumor (n = 5) and tumor regression (n = 5) upon oncogene inactivation." (PMID 31933479, 2020). "Vimentin and Twist1 positivity was observed in close proximity to necrotic areas in early passages and less commonly found at the centre of tumour ‘islands’." (PMID 33276802, 2020). "The transcription factor Twist1, which is known to promote tumor metastasis and induce the EMT, was obviously reduced when HEY1 was knocked down." (PMID 32025208, 2020). "We propose as a possible general explanation for our findings that overexpression of MYC and TWIST1 in a tumor is activating an embryonic program of innate immune cell activation and cellular invasion." (PMID 31933479, 2020). "Here, we showed that loss of PER2 enhanced tumor invasion by activating transcriptional genes of EMT, including TWIST1/2, ZEB1/2, and MMP1, suggesting a wide-range influence of PER2 on EMT process." (PMID 32185221, 2020). "We sought to ask if the expression levels of Twist1 correlate with levels of (i) EMT-associated genes, (ii) CIN genes, (iii) DNA double-strand break (DSB) genes and (iv) tumor mutation burden and copy number alterations (CNAs)." (PMID 32337580, 2020). "We determined if MYC and TWIST1 in human tumors cooperated to influence the tumor microenvironment through CIBERSORT analysis of 10,366 tumors from the human pan-cancer TCGA study." (PMID 31933479, 2020). "Our recent identification of Twist1 as a master regulator of tumor-induced cachexia provides a promising therapeutic target to attenuate cachexia to improve cancer patient survival." (PMID 32655411, 2020). "PDGF-D can promote tumor angiogenesis of colorectal cancer by activating Notch1/Twist1 signaling and recruiting macrophages to tumor tissues." (PMID 32993787, 2020). "Noteworthy, the tumor in the present study had both a high number of cells expressing TWIST-1 and a very low number of cells expressing membranous E-cadherin or, interestingly, the cells exhibited cytoplasmic internalization of the protein." (PMID 33297475, 2020). "Among the EMT-transcription factors, Twist1 induces the EMT in cancer cells resulting in tumor progression and invasion." (PMID 32685483, 2020).
tumor (continued). "(g) Comparison of liver weights between MYC (n = 3) and MYC/Twist1 tumor bearing mice (n = 4) and control mice (n = 3) which were kept on Dox throughout (**p<0.01)." (PMID 31933479, 2020). "For example, a study on Twist1 shows it is essential for initiate of skin tumorigenesis, however, Twist1 controlled tumor stemness independently of its EMT function." (PMID 32850862, 2020). "We found that MYC and TWIST1 drive metastasis by eliciting a transcriptional program in cancer cells that induces cytokines that in turn enable crosstalk between tumor and host, thus eliciting the recruitment and polarization of macrophages." (PMID 31933479, 2020). "Considered together, our data support the notion that the tumor suppression activities of miR-145-5p on TWIST1 translation are regulated by the fine-tuning of CPEB1 expression levels in a context-dependent manner." (PMID 33227047, 2020). "Accordingly, anti-IL-3R-EV treatment led to the downregulation of TWIST1, both in vitro and in tumor tissues." (PMID 33040091, 2020). "Conversely, the inactivation of MYC and Twist1 in tumors shows rapid and complete tumor regression in all observed mice (n = 20) within 2 weeks and also prompt exodus of macrophages." (PMID 31933479, 2020). "This shows that Twist1 expression is evident in many primary tumors, and that their level varies within and between cancer types, likely due to the cell-of-origin and tumor stage." (PMID 32337580, 2020). "Next, the effect of constitutive Twist1 overexpression on the DHR-induced suppression of CAF tumor-supporting capacity was evaluated by indirect co-culture experiments using conditioned medium from SCAF#36-WT or SCAF#36-Twist1 O/E(overexpression) cells." (PMID 32341496, 2020). "Primary tumor-derived cell lines which conditionally express MYC or MYC/Twist1 were re-introduced in vivo either by orthotopic transplantation into the liver or intravenous injection." (PMID 31933479, 2020). "It is important to emphasize that the apparent survival benefit of these experimentally induced tumor models (due to suppression of Twist1 activity) was mostly related to the reversal of muscle cachexia, and not due to shrinkage of tumor." (PMID 32655411, 2020). "In contrast, when p62 is overexpressed together with TWIST1 in A431 cells, an increase in cell migration, tumor growth and metastasis is observed, proposing a functional link between p62/TWIST1 in promoting pro-tumorigenic effects in vivo." (PMID 33634029, 2020). "More recently, few studies revealed the direct and indirect role of TWIST1 in the inhibition of a tumor suppressor E-cadherin." (PMID 34466597, 2020). "Twist1 is a well-known regulator of transcription during tumor initiation, stemness, angiogenesis, invasion, and metastasis." (PMID 32563267, 2020). "Instead, metastatic progression was dependent on the ability of MYC and Twist1 to dramatically reprogram the tumor innate immune microenvironment." (PMID 31933479, 2020). "Twist1 has multiple pro-cancer roles such as tumor initiation, cell proliferation, development of resistance to anti-cancer drugs, and inhibition of apoptosis." (PMID 32296610, 2020). "(h) Quantification of F4/80 staining in early tumor vs late tumor vs regressed MYC/Twist1-HCC (**p<0.01)." (PMID 31933479, 2020). "In order to establish the clinical relevance of these results, we next explored Twist1 expression in human OS tissue samples, revealing a significant increase in Twist1 expression in tumor tissues relative to paired normal control tissues." (PMID 32391253, 2020). "Positive nuclear Twist1 expression was seen only in EDW01 xenograft tumours, adjacent to regions of necrosis (as indicated by black arrows); however, nuclear Twist1 positivity did not increase in abundance across the passages." (PMID 33276802, 2020).
tumor (continued). "To perform our studies, we have generated the first autochthonous transgenic mouse model of HCC metastasis by hepatocyte-specific expression of MYC and Twist1 that will be useful to study tumor progression and identify new therapies." (PMID 31933479, 2020). "Previous studies have verified that the downregulation of Twist1 is related to induction of E-cadherin, and Twist1 inactivation suppressed tumor metastasis by regulating epithelial-mesenchymal transition (EMT)." (PMID 32549788, 2020). "A cadherin switch and an intermediate filaments rearrangement within primary site tumor cells together with the expression of the EMT-related transcription factors TWIST-1, ZEB-1, and HIF-1α were observed." (PMID 33297475, 2020). "Targeting TWIST1 or TWIST1-related molecules significantly inhibits tumor growth and cancer cell invasion and metastasis as well as reverses drug resistance, thus improving the survival of cancer patients." (PMID 32565805, 2020). "We further compared the mRNA expression of CDH1, CDH2, SNAI1, SNAI2, VIM, TWIST1 between ccRCC tumor samples and adjacent normal tissues respectively based on RNA-sequence data from TCGA database." (PMID 31915310, 2020). "In regard to tumor metastasis, HIFs are directly enrolled in tumor cellular growth by upregulating survival and proliferation genes, such as twist-related protein 1 (TWIST1), integrins αvβ3, αvβ5 and αvβ6, and several cadherins." (PMID 31893312, 2020). "FOXF2 can inhibit the EMT programme of tumour cells by repressing Twist1 transcription, thereby reducing the metastatic capacity of BLBC cells." (PMID 32503970, 2020). "Within the context of CSC, TWIST (twist family bHLH transcription factor 1) arose as a very promising candidate due to its important and well-known role in tumor invasion, migration, dissemination, and drug resistance." (PMID 31357505, 2019). "The protein expression of Src-1 or Twist1 in tumor tissues of NPC patients was apparently overexpressed comparing with paired adjacent normal tissues." (PMID 30973923, 2019). "MEIS1 silencing resulted in suppression of the involved genes in cell proliferation (EGF) and EMT (TWIST1), leading to tumor cell differentiation in ESC cell line KYSE‐30." (PMID 31090196, 2019). "The correlation between these characteristics and the clinical variables of the patients revealed an association between TWIST1 overexpression with lymph node status (chi-square; p = 0.036) and HER2 status of the primary tumor (chi-square; p = 0.006)." (PMID 31261917, 2019). "The expression of the TWIST1-ceRNET components was also detected by RT-PCR analysis of 38 paired fresh LUAD patients’ tissue samples (tumor and adjacent normal lung tissue samples)." (PMID 31645542, 2019). "TWIST1 was also observed in all tumor types, mostly with cytoplasmic immunopositivity and occasionally with nuclear expression, but without statistical significance." (PMID 31655611, 2019). "The mRNA expression of Src-1 and Twist1 in tumor samples and adjacent normal tissues of the 134 NPC patients was evaluated by qRT-PCR." (PMID 30973923, 2019). "Consistent with the in vitro findings, the PLCε- and Twist1-depleted groups both displayed less prominent tumorigenesis than the sh-NC group; the mean tumor volumes and weights were both lower in the PLCε- and Twist1-depleted groups than in the sh-NC group." (PMID 31383001, 2019). "When Twist1 and TP were individually or both overexpressed, tumor growth and lung metastasis were significantly enhanced." (PMID 30674871, 2019). "The GEO, The Cancer Genome Atlas, and the GTEx databases were used to determine Twist1 mRNA levels in tumors and their non-tumor counterparts." (PMID 31383001, 2019). "We used our own LUAD tissue microarray containing 92 pairs of LUAD and matched non-tumor tissue samples with clinicopathologic information and long-time follow-up records to evaluate the clinical utility of TWIST1, SLC12A5 and ZFHX4 among the LUAD patients." (PMID 31645542, 2019).